MIF (macrophage migration inhibitory factor)
Diseases named in the same sentence as MIF in open-access papers (continued):
Sharing a sentence is not in itself a finding about the gene and the disease.
gastric cancer (continued). "MIF inhibitors (such as IPG1576) can reduce MDSC differentiation, while the LGALS9-CD45/SPP1-CD44 axis promotes Macro_C1QC infiltration and CD8+T cell exhaustion, and the CXCL16-CXCR6 axis drives T cell functional failure and gastric cancer metastasis." (PMID 40740771, 2025). "By inhibiting MIF signaling, the TME characteristics of gastric cancer may be reversed, leading to the transformation of cold tumors into hot tumors." (PMID 37649598, 2023). "To further investigate whether MIF is responsible for TAM polarization and gastric cancer cell invasion induced by MAPK4 downregulation, we first examined MIF expression and TAM polarization in an orthotopic tumor model." (PMID 36797541, 2023). "Quantitative RT‒PCR revealed that the MIF mRNA levels remained invariable regardless of the knockdown or ectopic expression of MAPK4 in gastric cancer cells." (PMID 36797541, 2023). "Inhibition of the MIF signaling pathway in the TME and GPX4 expression in tumor cells may be an important strategy for cold tumor synergistic immunotherapy for gastric cancer." (PMID 37649598, 2023). "Moreover, TAMs activate epithelial–mesenchymal transition of gastric cancer cells to suppress MAPK4 expression, which further increases MIF secretion to polarize TAMs." (PMID 36797541, 2023). "MiR-451 was downregulated in gastric cancer, and its proved target were GATA2, ABCB1, MIF." (PMID 30736753, 2019). "The role of macrophage migration inhibitory factor (MIF) and autophagy in gastric cancer is not clear." (PMID 30742638, 2019). "Receiver operating characteristic curves for the discrimination between gastric cancer patients and the non-cancer controls were constructed based on serum levels of CEA, HNPs 1–3 and MIF." (PMID 19550422, 2009).
colon carcinoma (39 papers, 2010 to 2025). "High-level gastrointestinal expression of MIF in human is associated with occurrence of several diseases such as gastritis, gastric malignancy, gastritis ulcer, colon cancer and ulcerative colitis." (PMID 38468924, 2024). "Consistently, MIF expression is significantly correlated with susceptibility of colon cancer cells to hypoxia-induced apoptosis." (PMID 35842634, 2022). "Taken together, our results attest an upregulation of MIF expression in cetuximab-resistant colon cancer cell associating, for the first time, MIF dysregulation to cetuximab drug resistance." (PMID 31557914, 2019). "Increased MIF expression is also observed in human colorectal adenomas, and MIF deficiency reduces tumor incidence and angiogenesis in the ApcMin/+ model of colon cancer, providing direct evidence for its role in colon carcinogenesis." (PMID 26352431, 2015). "High serum levels of MIF have been suggested to be a diagnostic and prognostic factor for both gastric and colon cancers." (PMID 24887129, 2014). "Other groups have shown MIF to be a potential diagnostic or prognostic marker in gastric and colon cancers." (PMID 24887129, 2014). "Contradictory results also exist for colon cancer patients with one study showing that MIF expression was associated with tumor grade and hepatic metastases and another indicating that the elevated MIF expression correlated with better survival in Dukes C or D colorectal tumors." (PMID 32155795, 2020). "In brief, we previously identified that MIF binds to the molecular chaperone heat shock protein 90 (HSP90), resulting in hyperstabilization of MIF in epithelial cells, including colon cancer cells." (PMID 40835826, 2025). "Targeting SRC-3 with bufalin resulted in reduced polarization of pro-tumorigenic M2 macrophages by decreasing MIF expression in chemo-resistant colon cancer models." (PMID 38683834, 2024). "A relationship between MIF/E2F/Rb has been described, whereby human colon cancer cells were transfected with either sense- or anti-sense MIF-encoding plasmids." (PMID 36672343, 2023). "In contrast, overexpression of PCSK9 significantly increased MIF protein levels in colon cancer cells." (PMID 36242053, 2022). "Neutralization of MIF is reported to inhibit PD-L1 expression in colon cancer-bearing mice, thereby suppressing tumor progression." (PMID 35842634, 2022). "In contrast, levels of lactate, protein lactylation and MIF protein were significantly enhanced in colon cancer cells after PCSK9 overexpression." (PMID 36242053, 2022). "MIF promotes tumor growth by increasing Tregs production through modulation of IL-2 in a colon cancer model mouse model." (PMID 35842634, 2022). "Higher expression of MIF has been reported in different cancers, including endometrial cancer, lung adenocarcinoma, hepatocellular carcinoma, colon cancer, and NPC." (PMID 34407796, 2021). "LSECs secrete fibronectin that can induce EMT in colon cancer cells by enhancing ERK signalling, and human LSECs were shown to induce cell migration and EMT via MIF, thereby increasing the metastatic potential of colon cancer cells." (PMID 33669775, 2021). "MIF expression can be upregulated in response to growth factors and promote cell proliferation of colon cancer cells (colon-26) and, according to our results, in the active regenerative colonic epithelium." (PMID 31360118, 2019). "Our results provide new insights on the MIF capability of promoting cetuximab resistance in sensitive colon cancer cells." (PMID 31557914, 2019). "In these drug-resistant colon cancer cell populations, MIF was identified as the critical autocrine CXCR4 ligand promoting the invasive potential." (PMID 31557914, 2019). "Over the last decade, multiple roles for MIF have been also reported in promoting colon cancer development and progression." (PMID 31557914, 2019).
colon carcinoma (continued). "Along this line of research, it was shown that the growth rate of CT26 colon carcinoma cells was significantly lower in MIF knockout (MIF(-/-)) mice than in wild-type (MIF(+/+)) mice." (PMID 29707160, 2018). "In this study, we have shown that LPA increases MIF expression in colon cancer cells and its regulation is dependent on the transcription activation by HIF1α." (PMID 26352431, 2015). "Loss of LPA2 results in decreased expression of MIF in a rodent model of colon cancer, but the mechanism of MIF regulation by LPA is yet to be determined." (PMID 26352431, 2015). "Colitis-induced colon cancer in LPA2-null mice is associated with a marked decrease in cyclooxygenase-2, monocyte chemoattractant protein 1, and MIF." (PMID 26352431, 2015). "We found MIF to be highly produced by these cells compared to those from uninvolved tissues from the same patient in both gastric and colon cancers." (PMID 24887129, 2014). "We also found that patient gastric and colon tumors expressing the highest levels of MIF and CD74 to be from patients with nodal involvement, thus suggesting an association with more aggressive disease." (PMID 24887129, 2014). "To further implicate MIF in gastric and colon cancers, we examined MIF expression in human tumor tissues." (PMID 24887129, 2014). "In both gastric and colon cancer, patients who had nodal involvement had substantially higher expression of MIF at the mRNA level." (PMID 24887129, 2014). "These markers are cancer antigen 19-9 (CA19-9), also known for pancreatic, gastric and colon cancer, α-fetoprotein (AFP), also known for ovary, testis and liver cancer, and migration inhibitory factor (MIF), also known for gastric, prostate, and colon cancer." (PMID 23202969, 2012). "We reported that MIF plays a critical role in tumor growth and angiogenesis, as assessed by in vivo and in vitro studies using colon cancer cells." (PMID 23050964, 2012). "We utilized the proteomic analysis to demonstrate that the reduction of PCSK9 expression in colon cancer cells induced differentially expressed proteins that were mainly enriched in cellular and metabolic processes, while level of MIF expression had a significant trend for decline." (PMID 36242053, 2022). "Particularly, as chronic exposure to MIF has been shown to promote gastric and colon cancer, it might be an important link between chronic inflammation and tumorigenesis of the gastrointestinal tract." (PMID 31284478, 2019). "Similarly, anti-MIF monoclonal antibodies ameliorated the course of the disease in a CT26 colon cancer model." (PMID 29707160, 2018). "In this study, we show that LPA transcriptionally regulates MIF expression in colon cancer cells." (PMID 26352431, 2015). "To determine whether the LPA-LPA2 axis is directly responsible for MIF expression, we determined MIF expression in human colon cancer HCT116 cells." (PMID 26352431, 2015). "A previous study has reported that LPA induces MIF in CT26 rodent colon cancer cells." (PMID 26352431, 2015). "A few studies have suggested that MIF may be involved with tumor progression, one showing that MIF induces invasion of colon cancer cells in vitro in assays using matrigel." (PMID 24887129, 2014). "Similarly, colon tumor growth in our model, greatly coincides the growth recorded in MIF−/− mice." (PMID 25050663, 2014). "Furthermore, reduced growth of CT26 colon tumors (by 75%) in MIF−/− mice was reported." (PMID 25050663, 2014). "In colon cancer cells, the knockdown of proprotein convertase subtilisin/kexin type 9 (PCSK9) reduces both macrophage migration inhibitory factor (MIF) expression and lactylation levels, thereby promoting macrophage M1-type polarization." (PMID 40421024, 2025). "PCSK9 plays a crucial role in the progression and metastasis of colon cancer by regulating tumor cell EMT and the PI3K/AKT signaling pathway, and by mediating MIF and lactate levels to control macrophage phenotype polarization." (PMID 38714539, 2024).
colon carcinoma (continued). "MIF/CXCR4 axis were reported to induce an aggressive phenotype by inducing proliferation, adhesion, migration, and invasion of the colon cancer cells." (PMID 36417130, 2023). "PCSK9 played an important role in the progression and metastasis of colon cancer by regulation of tumor cell EMT and PI3K/AKT signaling and in the phenotypic polarization of macrophages by mediating MIF and lactate levels." (PMID 36242053, 2022). "MIF is a known target of HIF1α, and we have shown recently that LPA induces HIF1α in colon cancer cells under normoxic conditions." (PMID 26352431, 2015). "MIF and its receptor, CD74, were examined in gastric and colon tumors and found to be increased in most tumors with significantly higher expression in tumors from patients with lymph node metastasis." (PMID 24887129, 2014). "In this context, antisense MIF/SPG complex therapy is clinically meaningful for prevention of IBD and colon cancer." (PMID 23050964, 2012). "According to these results, we performed Western blot to confirm expression of MIF proteins after knockdown of PCSK9 in HCT116 and HT-29 cells and found that PCSK9 knockdown in colon cancer cells significantly decreased MIF expression, consistent with the results of our proteomic analysis." (PMID 36242053, 2022). "In addition, previous study has shown that the macrophage migration-inhibitory factor (MIF), MIF-CXCR4 axis is important in drug resistant colon cancer cells as the critical autocrine CXCR4 ligand." (PMID 27668882, 2016). "Although MIF is necessary for LPA-mediated colon cancer cell proliferation, how MIF facilitates this effect is not clear." (PMID 26352431, 2015). "Thus, an anti-MIF strategy for IBD treatment is advantageous not only for suppression of intestinal inflammation, but also for prevention of the colon cancer often seen at the late stage of IBD." (PMID 23050964, 2012). "In brief, murine colon cancer cells (cell line colon-26) were inoculated subcutaneously into the right flank of BALB/c mice, and the volume of the resulting tumors was drastically reduced by administration of anti-MIF antibody." (PMID 23050964, 2012). "Moreover, colonic tumor organoids lacking MIF exhibited reduced growth and diminished sensitivity to HSP90 inhibition, supporting the concept that MIF is a critical HSP90 client protein in CRC." (PMID 40835826, 2025). "Considering that both lactate and MIF regulate antitumor immunity and play a role in tumor microenvironment, we analyzed PCSK9 in regulation of TAMs polarization and found that PCSK9 was able to alter TAMs polarization in order to change the functions of TAMs in colon cancer." (PMID 36242053, 2022).
hepatocellular carcinoma (39 papers, 2009 to 2026). A malignant tumor that arises from hepatocytes. "We argue that both polymorphisms imply MIF as a central player in the progression of fibrosis, cirrhosis, and the risk for hepatocellular carcinoma in a context-dependent manner." (PMID 31370326, 2019). "In hepatocellular carcinoma, a positive correlation was also identified between intratumoral MIF and plasma MIF, suggesting that high tumor-associated MIF expression may drive higher circulating levels of soluble MIF." (PMID 33324425, 2020). "Gui-Qi Zhu reported that CD36+ CAFs in hepatocellular carcinoma exhibit high lipid metabolism and secrete macrophage migration inhibitory factor via the lipid peroxidation/p38/CEBPs axis, leading to an immunosuppressive TME and tumour stemness." (PMID 38316848, 2024). "Tumoral MIF protein expression has been shown to be correlated with plasma MIF cytokine levels in hepatocellular carcinoma." (PMID 38730725, 2024). "CAFs within hepatocellular carcinoma can also recruit M-MDSCs to hepatocellular carcinoma tissues by promoting macrophage migration inhibitory factor (MIF) secretion in a CD36-dependent manner." (PMID 38609997, 2024). "MIF stimulates the proliferation of hepatocellular carcinoma cells, such as Hepa 1–6 and HepG2 cells." (PMID 37784249, 2023). "Studies have also shown that MIF promotes hepatocellular carcinoma progression by regulating the immune microenvironment." (PMID 37784249, 2023). "Studies have revealed that EZH2 elevates hepatocyte growth factor (HGF) and macrophage migration inhibitory factor (MIF) in hepatocellular carcinoma, which contribute to M2 repolarization and poor prognosis." (PMID 36038549, 2022). "In an earlier study, MIF gene knockout was shown to enhance the expression of apoptosis-related proteins, including Bcl-2, p-caspase-3 and Bax, in hepatoma cells." (PMID 35842634, 2022). "By using a murine in situ hepatoma model, we further demonstrated that MIF contributes to anti-hepatoma activity of ConA by regulating STAT3–MIF–BNIP3-dependent autophagy." (PMID 26633714, 2015). "The increased MIF expression and secretion lead to autophagy through BNIP3 expression and LC3 conversion, which eventually causes hepatoma cell death." (PMID 26633714, 2015). "To further confirm the requirement of MIF in ConA-induced cell death of hepatoma cells, we generated MIF knockdown cell lines of HuH-7 and Hep G2 using short hairpin RNA (shRNA)." (PMID 26633714, 2015). "In summary, our findings uncover a novel role of MIF in lectin-mediated anti-hepatoma activities by regulating autophagy." (PMID 26633714, 2015). "We demonstrated that cell death is followed by an increment in MIF expression and secretion in the ConA-stimulated human hepatoma cell lines, HuH-7 and Hep G2." (PMID 26633714, 2015). "Nevertheless, MIF indeed is required for the ConA-triggered autophagic cell death of hepatoma cells in vivo." (PMID 26633714, 2015). "Knockdown of endogenous MIF by small hairpin RNA confirmed that MIF is required for both ConA-induced autophagy and death of hepatoma cells." (PMID 26633714, 2015). "Mechanistic in vitro experiments in oleic acid/IL-β stimulated mouse hepatoma cells Hepa1-6 and primary murine hepatocytes showed that recombinant MIF reduced hepatocyte lipid content through a CD74 and AMPK-mediated pathway." (PMID 26124760, 2015). "In our in situ hepatoma murine model, we demonstrated that the inhibition of MIF by ISO-1 abrogated the therapeutic effect of ConA in BALB/c mice." (PMID 26633714, 2015). "Our results indicate that MIF is required for ConA-induced autophagic cell death of hepatoma cells and anti-tumor activities in mice." (PMID 26633714, 2015). "We used rMIF to treat a human hepatoma cell line HuH-7 cells to determine if MIF can induce autophagy." (PMID 22629429, 2012).
hepatocellular carcinoma (continued). "Furthermore, CD36+ cancer-associated fibroblasts (CAFs) employ MIF and CD74 to attract CD33+ myeloid-derived suppressor cells (MDSCs), creating an immunosuppressive environment that facilitates immune evasion in hepatocellular carcinoma." (PMID 40051627, 2025). "In addition, MIF has been recognised as a crucial controller of the infiltration of mononuclear phagocytes in hepatocellular carcinoma." (PMID 39187937, 2024). "For example, intratumoral MIF is increased—versus normal tissue—three- and five-fold in endometrial carcinoma and non-small cell lung carcinoma, respectively, ten times in hepatocellular carcinoma and sixty times in colorectal cancer." (PMID 33324425, 2020). "As MIF can trigger autophagy in human hepatoma cells, we tested whether MIF is involved in ConA-induced autophagic cell death." (PMID 26633714, 2015). "In addition, ConA-induced autophagy and cell death of hepatoma cells were blocked in the presence of an MIF inhibitor." (PMID 26633714, 2015). "As ConA induced hepatoma cell death through autophagy, we next examined whether MIF regulates ConA-induced cell death via autophagy." (PMID 26633714, 2015). "A previous study revealed that MIF induces autophagy through ROS generation in hepatoma cells." (PMID 25617421, 2015). "As ConA internalization into cells is required to trigger autophagy in hepatoma cells, we next tested whether ConA internalization was also required to induce MIF secretion and thereby facilitate autophagy formation." (PMID 26633714, 2015). "However, few studies have focused on the clinical relevance of MIF and cyclin D1 expression in hepatocellular carcinoma cells (HCCs)." (PMID 25015194, 2014). "Here, we have demonstrated that incubation of human hepatoma cell line HuH-7 cells with recombinant MIF (rMIF) induced reactive oxygen species (ROS) production and autophagy formation, including LC3-II expression, LC3 punctae formation, autophagic flux, and mitochondria membrane potential loss." (PMID 22629429, 2012). "Overexpression of MIF has been reported in prostate, breast, colon and hepatocellular carcinomas." (PMID 19550422, 2009). "MIF also contributes to hepatocellular carcinoma (HCC), as evidenced by the -173 GC/CC SNP correlating with elevated circulating MIF levels and worse prognosis." (PMID 38732068, 2024). "Therefore, MIF is required for the ConA-induced autophagic cell death of human hepatoma cells." (PMID 26633714, 2015). "Furthermore, an in situ hepatoma murine model strengthened our hypothesis that MIF has an important role in ConA treatment by regulating autophagy." (PMID 26633714, 2015). "The interaction of MIF and CD74 was reported to exert proproliferative and antiapoptotic effects in murine hepatocellular carcinoma." (PMID 35634447, 2022). "As macrophage migration inhibitory factor (MIF), which is a proinflammatory cytokine, can trigger autophagy in human hepatoma cells, the possible involvement of MIF in ConA-induced autophagy was investigated in this study." (PMID 26633714, 2015). "The aim of the present study was to evaluate whether MIF could be used as a marker for hepatocellular carcinoma (HCC) detection." (PMID 21438767, 2011). "In this study, we demonstrated that the ConA-induced autophagy of hepatoma cells was inhibited and cell death was rescued in the absence of MIF or the presence of MIF inhibitor." (PMID 26633714, 2015). "Indeed, treating hepatoma cells with recombinant human MIF (rMIF) directly induced BNIP3 expression but not STAT3 phosphorylation, which were activated by ConA." (PMID 26633714, 2015).